ABCB1 (ATP binding cassette subfamily B member 1)
Diseases named in the same sentence as ABCB1 in open-access papers (continued):
Sharing a sentence is not in itself a finding about the gene and the disease.
schizophrenia (16 papers, 2011 to 2026). A major psychotic disorder characterized by abnormalities in the perception or expression of reality. "The objective of this study was to explore the correlation between DRD2, HTR2A, SLC6A4, CYP1A2, and ABCB1 polymorphisms and clozapine response in 100 patients with Treatment-Resistant Schizophrenia." (PMID 38540209, 2024). "We also previously reported associations of ABCB1 gene polymorphisms with ANS dysfunction following treatment with aripiprazole in patients with schizophrenia." (PMID 30016952, 2018). "Our results suggest that clinicians should bear in mind a higher risk of ANS dysfunction in patients with schizophrenia who are ABCB1 rs1045642 T allele carriers and rs2235048 C allele carriers and under aripiprazole treatment." (PMID 30016952, 2018). "ABCB1 rs2235048 has been associated with the efficacy of risperidone and paliperidone in schizophrenia." (PMID 30016952, 2018). "Moreover, ABCB1 2677G>T/A and 3435C>T polymorphisms were shown to influence risperidone-induced weight gain in patients with schizophrenia." (PMID 33240086, 2020). "However, few studies have investigated the effects of ABCB1 gene polymorphisms on ANS dysfunction due to several other atypical antipsychotics in schizophrenia." (PMID 30016952, 2018). "Mechanistic reviews highlight that cytokine-driven suppression, oxidative damage, and endothelial distress—common features of schizophrenia—can significantly inhibit ABCB1 transcription." (PMID 41465144, 2025). "Beyond their pharmacokinetic influence, both ABCB1 and ABCC1 participate in glutathione-dependent detoxification and oxidative stress responses—pathways strongly implicated in the neurobiology of schizophrenia." (PMID 41465144, 2025). "ABCB1 gene expression showed a similar pattern, with significant differences between patients with schizophrenia and the control group." (PMID 41465144, 2025). "Dysregulation of transporters such as ABCC1, ABCB1, and ABCA2 has been linked to neuropsychiatric disorders, yet their expression patterns in schizophrenia and their modulation by antipsychotic treatment remain unclear." (PMID 41465144, 2025). "Adult patients with schizophrenia will be randomized (2: 1) to receive PGx-assisted treatment (drug and regimen selection depending on the results of single-nucleotide polymorphisms in genes DRD2, HTR1A, HTR2C, ABCB1, CYP2D6, CYP3A5, and CYP1A2) or the standard of care." (PMID 38598465, 2024). "In contrast, previous candidate gene studies in Caucasian children with ASD and adults with schizophrenia have linked reduced RIS efflux with other ABC transporter subtype mutations (ABCG2_c.421C>A in ABCG2; c.3435C>T, c.1199G>A, c.1236C>T and c.2677G>T in ABCB1)." (PMID 38375040, 2024). "Literature-based analysis suggests that miR-9 exerts predominantly inhibitory effects on schizophrenia-related genes (e.g., IL1B, ABCB1, FGFR1) while promoting the expression of INS, indicating a potential protective role of miR-9 against schizophrenia." (PMID 40779062, 2026). "The present study aims to address this gap by examining the longitudinal expression patterns of ABCC1, ABCB1, and ABCA2 in individuals with schizophrenia before and after antipsychotic treatment, and by comparing these patterns with those of healthy controls." (PMID 41465144, 2025). "Our findings reinforce the need for future studies to more closely examine the relationship between SNPs in ABCB1 and ABCG2 and cannabis-related psychiatric problems such as addiction, schizophrenia and panic disorder." (PMID 22536451, 2012). "We did not detect a change in either ABCB1 or ABCC1 expression in people with schizophrenia nor in the context of high inflammation, which is in keeping with the fact that ABCB1 expression is only slightly reduced by IL-6 and increased by TNFα." (PMID 30214039, 2020).
schizophrenia (continued). "Collectively, these findings underscore the potential gene-specific heterogeneity of ABC transporter biology in schizophrenia: ABCC1 may relate to inflammatory variability, ABCB1 may reflect pharmacodynamic differences, and ABCA2 may index treatment-associated metabolic adaptations." (PMID 41465144, 2025).
bladder cancer (15 papers, 1994 to 2025). "A recent study revealed that suppressing ABCB1 improved the susceptibility of bladder cancer cells to cisplatin by reducing cytotoxic effects and promoting cell death in UBC cells treated with cisplatin." (PMID 36650399, 2023). "ABCB1, a well-known ATP-binding cassette transporter associated with cisplatin resistance in bladder cancer, is the gene with the highest differential expression after FOXC1 knockout." (PMID 35406487, 2022). "In the present study, we investigated the possible association between SNPs in the GSTP1, GSTO1, GSTO2, and ABCB1 genes with response to treatment in patients with bladder cancer." (PMID 26354850, 2015). "In urinary bladder cancer, the effects of the ABCB1 rs1128503 polymorphism on temsirolimus and its active metabolite sirolimus following administration were associated with an increased drug concentration (p = 0.037) and a prolonged sirolimus half-life (p = 0.010)." (PMID 36650399, 2023). "In a prior study, the overexpression of the ABCB1 gene, on the other hand, coincided with elevated cisplatin resistance, hindered cytotoxicity, and overall treatment resistance in bladder cancer patients." (PMID 36650399, 2023). "Direct suppression of the ABCB1 gene by miR-3682-3p contributed to cisplatin and gemcitabine resistance in patients with urinary bladder cancer." (PMID 36650399, 2023). "After compiling the data, we would like to first point out that suppressing the expression of the efflux transporters ABCB1, ABCC2, SLC25A21, and ATP7A has been linked to cisplatin’s accumulation and reduced resistance in urinary bladder cancer patients." (PMID 36650399, 2023). "ABCB1 mRNA levels were 3.5–5.7-fold higher in bladder cancers after chemotherapeutic treatment than those in untreated primary tumors." (PMID 33066132, 2020). "miR-34b-5p also facilitated the tolerance of bladder cancer cell to cisplatin via targeting ABCB1." (PMID 38581057, 2024). "However, no significant alterations in gene expression were detected for ABCB1 in bladder cancer cells." (PMID 35694719, 2022). "We concluded that the efflux transporters ABCB1, ABCC2, SLC25A21, ATP7A, and the uptake transporter OCT2, as well as the organic anion uptake transporters OAT1 and OAT2, are linked to cisplatin accumulation, toxicity, and resistance in urinary bladder cancer patients." (PMID 36650399, 2023). "The involvement of ABC transporters, particularly MDR1 (ABCB1), MRP1 (ABCC1) and BCRP (ABCG2), in resistance to traditional chemotherapy has been well established in bladder cancer." (PMID 39877564, 2025). "This transition leads to the downstream activation of regulated target genes, including ABCB1 and ID3, driving drug resistance in bladder cancer." (PMID 35406487, 2022). "miR-3682-3p directly suppressed ABCB1 gene, contributing to BMI1-mediated chemoresistance in bladder cancer cells." (PMID 34270461, 2021). "These experiments showed that miR-3682-3p could directly inhibit ABCB1 gene through targeting its 3'-UTR, contributing to BMI1-mediated chemoresistance of bladder cancer cells." (PMID 34270461, 2021).
sarcoma (15 papers, 1999 to 2023). A usually aggressive malignant neoplasm of the soft tissue or bone. "Lower levels of sarcoma CSC markers SOX2, NANOG, ALDH1A1, ABCB1 and ABCC1 were observed in silenced cells in 2D and in CSC-enriched cultures (single-cell and 3D/spheroid)." (PMID 35864381, 2022). "Recent findings from a phase I study revealed that the sequential administration of nilotinib prior to doxorubicin treatment led to a reduction in ABCB1 activity in sarcoma patients, without a corresponding increase in cardiotoxicity." (PMID 37762275, 2023). "Besides, CSC and drug-resistance related genes in sarcoma such as SOX2, NANOG, ALDH1A1, ABCB1 and ABCC1 were down-regulated in 2D, as well as in CSC-enriched cultures (colony-forming and 3D/ spheroid)." (PMID 35864381, 2022). "Others have also investigated the effects of single-step doxorubicin selection on the human sarcoma cell line MES-SA and have reported an increase in ABCB1 expression; yet previous studies were performed before the identification of ABCG2 as a major ABC transporter in the area of MDR." (PMID 18382425, 2008). "Moreover, in the analysis of undifferentiated pleomorphic sarcoma subgroup we demonstrated the negative correlation for the ABCB1 and ABCG2 expression and SI (Doc) or SI (Gem + Doc)." (PMID 35328603, 2022).
Stroke (15 papers, 2011 to 2025). Sudden impairment of blood flow to a part of the brain due to occlusion or rupture of an artery to the brain. "The polymorphism on ABCB1 3435C → T was correlated to a significant increase in adverse outcome including cardiovascular death, MI, or stroke (P = 0.0064)." (PMID 22135769, 2011). "While earlier works emphasized well-known inflammatory markers (e.g., IL6, TNF-α), we identified novel candidates (OAS2, TMEM106A, ABCB1) with limited prior links to atherosclerosis or stroke." (PMID 40371070, 2025). "Accumulating evidence suggests that ABCB1 transporters as well as MMP-9 activity are regulated by the nuclear factor-kappa B (NF-κB) signaling pathway under non-stroke conditions." (PMID 34483846, 2021). "Recent work from our group has established a causal link between increased activity of both ABCB1 and MMP-9 on the one hand and the NF-κB pathway on the other hand under stroke conditions." (PMID 34483846, 2021). "ABCB1 participates in the regulation of various pathological conditions including inflammation, heat shock and stroke." (PMID 34783294, 2021). "Patients on ticagrelor were less likely to experience stroke independently of CYP2C19 or ABCB1 genotype." (PMID 22135769, 2011). "The investigation into ABCB1 in the context of ischemic stroke is likely focused on understanding how this transporter protein may impact the efficacy of drugs used in stroke treatment." (PMID 38914966, 2024). "Both variants (CYP2C19*2 and ABCB1) were significant independent predictors of cardiovascular death, ACS, or stroke (ABCB1 3435 TT vs. CT/CC, HR 2.01, 95% CI: 1.30–3.11, p = 0.0017; CYP2C19 LOF alleles carriers vs. non-carriers, HR 1.77, IC95%: 1.11–2.80, p = 0.0155)." (PMID 30939847, 2019). "Whereas the role of NF-κB and the proteasome under stroke conditions has already been shown, the mutual interaction between MMP-9 and ABCB1 on the one hand and NF-κB on the other hand has just recently been described by us in a murine stroke model." (PMID 34483846, 2021). "The distribution of ABCB1 C3435T genotypes for patients with and without stroke." (PMID 23056288, 2012).
epidermoid carcinoma (14 papers, 2015 to 2025). "In conclusion, we found a significantly higher ABCB1 expression in esophageal adenocarcinomas than in squamous cell carcinomas, which might be causally related to a better treatment effectivity of paclitaxel in the latter." (PMID 34858183, 2021). "For example, it was shown that PD 173074, FGFR1 inhibitor, reversed ABCB1-mediated multidrug resistance to colchicine (CH), paclitaxel (PTX), and vinblastine (Vin) in CH-resistant human epidermoid carcinoma cell subline and ABCB1-overexpressing HEK293 cells." (PMID 35327403, 2022). "The single evaluable squamous cell carcinoma sample expressed ABCB1 moderately which also corresponds with the ABCB1 expression observed during the first cycle of chemotherapy." (PMID 34858183, 2021). "In this study, by gene knockout with CRISPR/Cas9 gene editing technique, we determined the regulation of CDK4 or CDK6 on ABCB1-mediated MDR in human epidermoid carcinoma MDR cell line KB-C2 which overexpresses ABCB1 and H460/MX80 which expresses ABCB1 at low level." (PMID 35459184, 2022). "Interestingly, ABCB1 expression was significantly higher in adenocarcinoma than in squamous cell carcinoma (p < 0.01)." (PMID 34858183, 2021). "However, we have also demonstrated a significantly higher expression of ABCB1 in adenocarcinoma than in squamous cell carcinoma of the esophagus." (PMID 34858183, 2021). "By single gene knockout using CRISPR/Cas9 technique in human epidermoid carcinoma MDR cell line KB-C2, we recently revealed that CDK6-PI3K signaling axis is an efficient target for attenuating ABCB1/P-gp mediated MDR in cancer cells." (PMID 35450042, 2022). "We have shown earlier that the human epidermoid carcinoma cell line A431 provides a reliable and stable model for the characterization of the function of MDR ABC transporters ABCB1 and ABCG2." (PMID 30863990, 2019). "qRT-PCR tests revealed that gemcitabine triggered a significant increase in ABCB1 and ABCC2 expression both in adeno and squamous cell carcinoma tissues while paclitaxel and doxorubicin differentially initiated drug transporter transcription." (PMID 28340578, 2017). "Indeed, Chen Z-S with colleagues demonstrated that PD 173074, FGFR1 inhibitor, reversed ABCB1-mediated multidrug resistance to colchicine, PTX, and vinblastine (Vin) in colchicine-resistant human epidermoid carcinoma cell subline and ABCB1-overexpressing HEK293 cells, as well." (PMID 35327403, 2022). "In addition, expression of ABC subfamily transporter proteins vary with clinical variables; for instance, ABCB1 expression is significantly higher in females than in males, and higher in non-squamous cell carcinoma than in squamous cell carcinoma in NSCLC." (PMID 26270652, 2015).
atrial fibrillation (13 papers, 2018 to 2025). A disorder characterized by an electrocardiographic finding of a supraventricular arrhythmia characterized by the replacement of consistent P waves by rapid oscillations or fibrillatory waves that vary in size, shape and timing and are accompanied by an irregular ventricular response. "According to a case report, an elderly patient having atrial fibrillation experienced bleeding that resulted from ABCB1 gene polymorphism." (PMID 39459499, 2024). "We reviewed 155 patients enrolled in the research to analyze the influence of ABCB1 gene polymorphism on rivaroxaban blood concentration and hemorrhagic events in patients with atrial fibrillation." (PMID 33935730, 2021). "We evaluated the functional response to dabigatran according to different CES1 and ABCB1 single-nucleotide polymorphisms (SNPs) in patients with atrial fibrillation (AF)." (PMID 38731074, 2024). "A case report showed that the ABCB1 gene mutation (rs1045642 and rs2032582) might lead to the prolonged half-life of rivaroxaban, which was related to the bleeding in an elderly patient with atrial fibrillation." (PMID 37420302, 2023). "We analyzed the genotype–phenotype relationship of ABCB1 (rs1045642, rs4148738, rs2032582, and rs1128503) and CES1 (rs8192935, rs71647871, and rs2244613) polymorphisms in patients with atrial fibrillation who had been treated with dabigatran." (PMID 39011438, 2024).
triple-negative breast carcinoma (13 papers, 2018 to 2025). An invasive breast carcinoma which is negative for expression of estrogen receptor (ER), progesterone receptor (PR), and human epidermal growth factor receptor 2 (HER2). "The analysis of the results showed that a decrease in the expression of the ABCB1 gene in patients diagnosed with triple-negative breast cancer is associated with the early stage of the disease and shorter survival of patients." (PMID 36674773, 2023). "Previous studies reported that MDR1 (ABCB1) and ABCC1 (MRP1) expressions in breast cancer are subtype-specific and associated with triple-negative breast cancer." (PMID 37239055, 2023). "The binding of UIC2–BPD to ABCB1 was demonstrated in lipidic nanodiscs and ABCB1-overexpressing triple negative breast cancer (TNBC) cells." (PMID 35070633, 2021). "In this study, we sought to devise a photoimmunoconjugate formulation that combines hydrophobic BPD photosensitizers and a conformation-sensitive UIC2 monoclonal antibody to identify ABCB1 expression on triple negative breast cancer (TNBC) cells." (PMID 35070633, 2021). "In models of multidrug-resistant, triple-negative breast cancer, jadomycin B has shown promise as it is not a substrate of ABCB1 and ABCG2 drug efflux transporters." (PMID 40253988, 2025). "Targeting ABCB1 and ABCC1 with tariquidar may be a promising strategy for reversing the acquired multidrug resistance of triple-negative breast cancer cells." (PMID 34208283, 2021).
liver cancer (12 papers, 1996 to 2025). An epithelial or non-epithelial malignant neoplasm that arises from the liver. "The ABCB1 are considered to be a prime factor for inducting multidrug resistance in liver cancer treatment." (PMID 34055017, 2021). "Our results also revealed an essential role of NF-κB in ERRγ-induced expression of ABCB1 and chemoresistance, which is further supported by clinical data confirming that expression of ABCB1 and ERRγ was positively correlated in liver cancer tissues." (PMID 32206097, 2020). "The NRF2/ABCB1-mediated efflux effect may lead to decreased intracellular uptake of doxorubicin, which results in chemoresistance in hypoxic liver cancer cells." (PMID 34060621, 2021). "Our in vitro experiments on ABCB1 and PGP expression utilized HepG2, an established cell line of human liver cancer origin." (PMID 36904118, 2023).
ovarian tumor (12 papers, 2009 to 2025). "We also observe elevated ABCB1 expression associated with paclitaxel resistance in primary ovarian tumor organoids underscoring potential clinical relevance." (PMID 34347777, 2021). "It is also known that HA-CD44 interactions activate a variety of signaling pathways (including the PI3K pathway) that contribute to stimulation of ABCB1 expression, leading to drug resistance in breast and ovarian tumor cells and bone tumor cells." (PMID 38672482, 2024). "Interestingly, in this study ER was found to be a substrate of ABCB1 in the Taxol-selected resistant ovarian tumor cells." (PMID 39859349, 2025). "In the current study, we took the opportunity to study ABCB1 in our primary ovarian tumor material." (PMID 19835627, 2009). "Increased levels of various transporters, such as ABCA1, ABCB5, and ABCC3/MRP3, have been demonstrated in ovarian tumour tissues, and an increased expression of ABCA1, ABCB1/MDR1/P-GP, and ABCG2/BCRP has been demonstrated in ovarian CSCs." (PMID 38201468, 2023). "ABCB1 expression was upregulated in paclitaxel-resistant TOV-21G (q < 1x10-300), OVCAR3 (q = 7.4x10-156) and novel ovarian tumor organoid (p = 2.4x10-4) models." (PMID 34347777, 2021). "ABCB1 is expressed in ovarian tumors which have been treated with paclitaxel, but not in chemonaive cancers or cancers exposed to other chemotherapy drugs such as cisplatin that are not substrates for ABCB1." (PMID 35582032, 2021).